IL6 (interleukin 6)
Diseases named in the same sentence as IL6 in open-access papers (continued):
Sharing a sentence is not in itself a finding about the gene and the disease.
tumor (continued). "IL10-modified hMSCs could also inhibit the growth of pancreatic cancer by inhibiting the secretion of pro-inflammatory cytokines IL6 and TNF-α and tumor angiogenesis." (PMID 35281017, 2022). "These soluble factors like IL-6, IL-10, IDO, M-CSF, TGF-β1, PGE2, VEGF present in TME reprogram DCs to possess inefficient antigen-presenting capabilities, and an immunosuppressive regulatory phenotype that supports tumor progression." (PMID 36253762, 2022). "Although the activation of the IL-6/STAT3 signal has been primarily identified as being necessary for the proliferation of several types of CSCs, tumor-derived erythropoietin, mainly released under hypoxic conditions, also activates the JAK2–STAT3 axis in breast CSCs and promotes self-renewal." (PMID 36010693, 2022). "Downregulation of miRNA-125b or inhibition of mitogen-activated protein kinase (MAPK) mRNA could restrain the p38/MAPK pathway and reduce IL-6 secretion, which suppresses GBM tumor cell migration and invasion." (PMID 35572545, 2022). "Tumor cells subsequently increase OXPHOS and decrease glycolysis via IL-6." (PMID 35563739, 2022). "This ICD induction increases the serum levels of proinflammatory cytokines, such as TNF-α, IL-6, and IFN-γ, while also improving the tumor infiltration of CD4+ and CD8+ cells, eradicating the primary tumor, and preventing lung metastasis through an abscopal effect." (PMID 35214129, 2022). "For example, the secretion of growth factors and cytokines by astrocytes can stimulate tumor cell growth, including astrocyte-derived interleukin 6 (IL-6), transforming growth factor-beta (TGFβ) and insulin-like growth factor 1 (IFG-1) which have been shown to increase tumor cell proliferation." (PMID 36230886, 2022). "IL-6 and G-CSF, also secreted by HPV-transformed cells, can activate STAT3 systemically, promoting the accumulation of myeloid cells, including neutrophils, which can then be recruited to the tumor microenvironment by chemotactic molecules, such as IL-8." (PMID 35804810, 2022). "In patients with advanced tumors, some inflammatory factors such as tumor necrosis factor alfa, interleukin 6, and interleukin 1 beta can induce the synthesis of CRP in hepatocytes while promoting angiogenesis to support tumor growth and anti-apoptosis capabilities to protect tumor cells." (PMID 36266627, 2022). "Both T cells and CAR-T20 cells resulted in a slight increase in murine TNF levels, while tumor burden, T cells and CAR-T20 cells could also introduce a mild increase in murine IL-6." (PMID 36352168, 2022). "Interleukin-6 (IL-6) is a pleiotropic pro-inflammatory cytokine and has been shown to serve as a negative prognostic parameter for several tumor entities including HNSCC." (PMID 34773163, 2022). "Importantly, the mean fluorescence intensity of either CD3 or CD8 were significantly reduced after EVs/IL6 were masked with anti-PD-L1, suggesting that the reduction of vesicular PD-L1 level activated the CD3+/CD8+ T cell function in tumor environment." (PMID 35692503, 2022). "In addition, activation of GPR68 caused the stimulation and secretion of proinflammatory mediators such as IL‐6 and IL‐8 (CXCL8), which triggered tumor progression." (PMID 35311103, 2022). "Importantly, IL6 and TNFA gene expression in cocultured Tcam-2 cells can be explained by contaminating monocytes that firmly stick to the tumor cell monolayer and cannot be completely removed prior to RNA extraction." (PMID 35269507, 2022). "IL-6 and the IL-6/JAK/STAT3 signalling pathway have a key role in the growth and development of many human cancers, and have been shown to drive cellular proliferation, survival, invasiveness, and metastasis of tumour cells." (PMID 36396670, 2022). "Co-cultivation of the two CCA cell lines HuCCT-1 and TFK-1 with CAF increased tumor cell migration and secretion of the pro-inflammatory cytokines MCP-1, CXCL-1, IL-6 and IL-8, which could be clearly diminished by Sorafenib treatment." (PMID 35628911, 2022).
tumor (continued). "A previous study reported that activation of the IL-6/JAK1 pathway could drive PD-L1 Y112 phosphorylation and result in the evasion of the immune system by tumor cells." (PMID 35550592, 2022). "Immunotherapy reduces tumor development in IL-6-/- mice with a significant improvement in survival but does not induce tumor remission." (PMID 36405719, 2022). "IL6/JAK/STAT3 signaling and TNFα signaling via NFκB were positively enriched in the active clusters, suggesting that cytokine signaling, likely from the microenvironment, triggers tumor cell awakening." (PMID 36008376, 2022). "High expression of these genes, which may indicate S1P export, correlated among others with immune signatures related to TNFα and IL6 signaling but also to allograft rejection and IFN-γ, which has anti-tumor properties." (PMID 35163211, 2022). "Bcl2, Bax, IL6, TNFα, CASP3, and other potential targets are related, and they may inhibit tumor growth and induce tumor cell apoptosis through AGE/RAGE and other signaling pathways." (PMID 35815259, 2022). "This review will focus on the role of IL-6 and IL-11, in particular, in driving increased STAT3 transcriptional activity in breast cancer, and how this leads to metastasis and immune evasion within the tumor microenvironment." (PMID 35053592, 2022). "Collectively, CTVTs spontaneously regress under an intact immune system with the IL-6 secretion from the TILs and the upregulation of the MHC class I and II molecules of tumours; the overexpression of MHC molecules triggers the immune system and eradicates the CTVTs." (PMID 34980125, 2022). "Further, the results of Western blot and ELISA demonstrated that the Erlotinib treatment led to increased levels of APE1, IL‐6 and p‐STAT3/STAT3 in tumour tissues, which could further be increased in response to HCC827R‐CSC‐EVs (all p < .01)." (PMID 35605028, 2022). "Both 1MT isomers lead to increased gDE7-mediated antitumor protection in WT mice, but only the combination of gDE7 with IDO inhibitors in the absence of IL-6 afforded more efficient tumor cell eradication." (PMID 36405719, 2022). "Upon binding to its receptors, IL-6 triggers the pathway and activates downstream molecules, such as STAT1 and STAT3, which may enhance the capacity of tumor cells to survive in a highly inflammatory environment and impair immunotherapy effects." (PMID 36119033, 2022). "The increased expression of proinflammatory cytokines (IL-6, TNFα, IL-1B) found here in the aggressive PCa-related PPAT supports the role of PPAT in aggravating the tumor microenvironment, either by direct effects on premalignant cells or by acting on the tumor microenvironment." (PMID 35978404, 2022). "Regarding the establishment of tumor-promoting inflammation, KRAS was shown to be capable of inducing cytokine secretion such as IL-6 and reduced secretion of IFNγ, TNF, and IL-2 by different stromal cell types, e.g., fibroblasts, myoblasts and epithelial cells." (PMID 35965494, 2022). "Numerous cytokines and chemokines known to enhance stromal activity such as TGFB1, TGFB2, TGFB3, CXCL12, CCL2 and IL-6 were found downregulated in 211F MEF cells, suggesting a potential tumor-promoting function of Y211 phosphorylation through regulation of the secretome in the stromal environment." (PMID 35628489, 2022). "Subsequently, macrophage-derived IL-6 activates STAT3 signaling and promotes EMT in tumor cells." (PMID 36071472, 2022). "CXCL8/IL8, ENA-78/CXCL5, IL6, and TERC/CCL25, both in double co-culture and triple co-culture, indicated the formation of a microenvironment with chronic inflammation characteristic of the tumor stroma and the active participation of MSCs in these processes." (PMID 36354566, 2022). "Significantly increased tumour inhibition was observed in mice receiving the combination treatment of antibodies, compared with mice receiving monotherapy of the specific antibodies (CTLA-4 p = 0.0207, interleukin-6 p = 0.0002)." (PMID 35626020, 2022).
tumor (continued). "We found that IL-6 induced STAT1 transcriptional activity upon STAT3 depletion, suggesting that HCC tumor cells may activate both STAT1 and STAT3 signaling under pro-inflammatory conditions." (PMID 35267462, 2022). "In particular, in PCa pSTAT-3 and IL-6R are present in 95% of metastatic niches of patients who die of castration-resistant PCa (CRPC); this suggests that in PCa, the activation of STAT-3 mediated by IL-6, IL-10 and EGF serves an important role for tumor progression and development of metastasis." (PMID 35703345, 2022). "When tumor cells are in low oxygen and low pH, they will release Neuropilin-1 (Nrp-1), TGF-β, IL6, IL4, Tim-3 to promote the transformation of macrophages into M2 type, which can help tumor cells to escape immune and secrete growth factors to enhance tumor growth." (PMID 36684237, 2022). "This further supports the idea that tumor-derived IL-6 promotes MDSC expansion and that blocking systemic IL-6 signaling could prove beneficial to cancer patients, so it should be further explored." (PMID 36142210, 2022). "Cytokine levels significantly correlated with tumor grade (IL-6; p = 0.0070), prevalence of distant metastasis (IL-18; p = 0.0313), and disease progression over time (IL-10; p = 0.0033) but not tumor location." (PMID 36294509, 2022). "Among the pro-inflammatory cytokines, IL-6, together with IL-1 and TNF-α, is one of the most relevant promoters of acute inflammatory response, also capable of reinforcing chronic phase inflammation, providing the favorable environment for tumor growth." (PMID 35406495, 2022). "Some studies have identified several molecular mechanistic pathways that may contribute to the tumor microenvironment changes after RFA, such as IL-6, HGF/c-Met and VEGF, which were considered relevant to tumor growth, metastasis, and invasion." (PMID 35710408, 2022). "Except for the effects we mentioned, norcantharidin also could inhibit the IL6-driven EMT, thus reducing the immune escapes of tumor cells." (PMID 36615387, 2022). "NF-kB-mediated factors like IL-6 and CCL2 prevent tumor cell apoptosis." (PMID 36246629, 2022). "Tumour-promoting inflammatory factors, including IL-6, LIF, and CXCL8, are mainly secreted by iCAFs but not myCAFs." (PMID 36284087, 2022). "Tumor-derived IL-6 phosphorylates STAT3 and stimulates two noncanonical NF-kB subunits, p52 and RelB to form a dimer that directly binds to the promoter of IDO1, then drives the expression of IDO1 in MDSCs." (PMID 35681736, 2022). "Systemic inflammation promotes the release of fibrinogen, which promotes tumor cell proliferation and metastasis by participating in extracellular matrix formation and inducing epithelial–mesenchymal transition via the p-AKT/p-mTOR pathway and IL-6 synthesis." (PMID 36387142, 2022). "IL-6 activates signal transducers and activators of transduction-3 (STAT3) to affect tumor-infiltrating immune cells, stimulate downstream target genes to protect tumor cells from apoptosis, facilitate tumor cell proliferation, upregulate tumor angiogenesis and drug resistance." (PMID 35222443, 2022). "Additionally, S1P–S1PR1 signaling activates STAT3 by upregulating IL-6 and JAK2 activity to promote tumor growth and metastasis." (PMID 35565311, 2022). "Furthermore, many tumor-derived cytokines such as FGF1, HIF-1, VEGF, IL-6, and G-CSF have been shown to promote the accumulation of MDSCs and are related to therapy resistance." (PMID 36457492, 2022). "While M2 macrophages display tumor-promoting activity and can be further classified into four different subtypes, M2a (induced by IL4, IL13), M2b (induced by TLR), M2c (induced by glucocorticoid), and M2d (induced by IL6 and adenosines)." (PMID 35186730, 2022). "TAF modifies the composition of the TME and the development of cancer, and both TAF secreted cytokines (such as CCl2, CXCL1, and IL-6) and ECM could drive the stemness of tumor cells." (PMID 35322024, 2022).
tumor (continued). "Another source of influence on tumor microenvironments is the capacity of photon beams to potentiate angiogenesis and lympho-genesis by stimulating the release of growth factors and other signaling molecules, notably VEGF, IL-6 and IL-8." (PMID 36675979, 2022). "This is because the IL-6/STAT3 pathway favors the immunosuppressive cells and dysregulates the T cell subsets, such as myeloid-derived suppressor cells (MDSCs) and T regulatory cells, leading to tumor progression." (PMID 35444660, 2022). "Studies have shown that IL6 and IL10 can directly or indirectly stimulate NK cell activity, thus exerting anti-tumor effects, which is consistent with previous studies indicating that NK cells are highly expressed in LCC and significantly correlated with the prognosis of patients." (PMID 35936748, 2022). "Compared with the control and Lmo treatments, the tumor‐bearing mice treated with Lmo@RBC displayed an obviously high level of IL‐6, IL‐1β, and TNF‐α in blood serum, which was attributed to the high‐efficiency tumor‐homing capability of Lmo@RBC to improve the therapeutic efficiency." (PMID 36266982, 2022). "The findings of the current study showed that FTO inhibited expression of APOE through IGF2BP2-mediated m6A modification and may inhibit glycolytic metabolism in PTC by modulating IL-6/JAK2/STAT3 signaling pathway, thus abrogating tumor growth." (PMID 35090515, 2022). "Hypoxia has no influences in regulating IL1A or IL6 expression in macrophages, but instead dramatically promotes their expression in the co-culture with tumor cells." (PMID 36071472, 2022). "According to this, we did also not observe any enhanced secretion of tumor cytokines (IL-6 and IL-8) which can also serve as measure for toxicity of nanoparticles." (PMID 35251021, 2022). "MRNA levels of CA12 exhibited positive correlations with those of HIF1A, TNF-A, IL-10, and IL-1B, but not those of IL-6, in tumor-derived monocytes." (PMID 35362480, 2022). "In this experiment, ABP treatment inhibited the phosphorylation of STAT3, reduced the expression of IL-6 and increased the expression of IL-10, indicating that the anti-inflammatory effect of ABP may be one of its anti-tumor effects." (PMID 35264966, 2022). "Some of the mediators that are recognized include tumor necrosis factor (TNF), vascular endothelial growth factor (VEGF), interleukin-6 (IL6), which has a key role as a growth factor for tumor cells, hepatocyte growth factor (HGF), and transforming growth factor beta (TGF-β)." (PMID 36362398, 2022). "Additionally, S1P can also activate HIF-1a, resulting in the production of VEGF and pro-tumour cytokines such as IL10 and IL6." (PMID 36497148, 2022). "Represented by IL-1 and IL-6, primary mediators of GBM tumor cells in the inflammatory TME can orchestrate immunological activation and inflammatory signaling cascades such as hypoxia-inducible factor-1α (HIF-1α), Wnt-1, nuclear factor-kappa B (NF-κB), and STAT3 in GBM." (PMID 35572545, 2022). "We have previously investigated the role of IL6 in regulating the inflammatory cytokine network found in HGSOC and in a series of ex vivo and human tumor xenograft experiments, found that this cytokine directly stimulated angiogenesis with defective pericyte coverage." (PMID 35313341, 2022). "Moreover, IL6 secretion by MM cells and by activated CD3 T cells in MM inhibits the polarization of naïve CD4 T cells into Th1 cells enabling tumor escape." (PMID 35954459, 2022). "Furthermore, the elevated inflammatory cytokine IL-6 can raise tumor progression and invasion in GBM, and high levels of IL-1β also activate GBM cells and promote IL-6 production." (PMID 35368876, 2022). "These suggest that CAF in tumor microenvironment promotes the progress of GC through IL-6/JAK2/STAT3 signal transduction, and IL-6 targeted therapy may become a complementary treatment for GC by acting on stromal fibroblasts." (PMID 36591515, 2022).
tumor (continued). "Relative to Control, Tumor mice had higher spleen mass, higher burden of total splenic bacteria as detected via FISH staining for global bacterial 16S DNA, and higher splenic production of the pro-inflammatory cytokines IL-6, CXCL1, and MCP-1, but lower TNFα." (PMID 35248004, 2022). "Moreover, Artemisia argyi polysaccharides (FAAP-02) were reported to improve anti-tumor activity by promoting the production of lymphocyte, TNF-α, IL-2, IL-4, IL-6, and IL-12." (PMID 35295918, 2022). "For example, it has been reported that inhibition of the IL-6-JAK/STAT-3 signaling pathway in CRPC cells (C4-2 and CWR22Rv1) sensitizes tumor cells to NK cell-mediated cytotoxic action through changes in the PDL-1 ligand interaction and the expression of NKG2D." (PMID 35465350, 2022). "In addition, pro-inflammatory cytokines (e.g., IL-6, TNF-α, and IL-1β) induced by ICD, can also help convert an immunosuppressive tumor microenvironment into an immunogenic one." (PMID 36278159, 2022). "When comparing different tumour types, IL-6 seems to be widely expressed by CAFs in many, if not in virtually all, cancer types." (PMID 35055153, 2022). "Importantly, IL-8 and IL-6 play crucial roles in promoting CRC migration and metastatic processes in addition to the tumor microenvironment and inflammation." (PMID 36139106, 2022). "After recognizing the tumor antigen, CAR-T cells release proinflammatory cytokines including interleukin (IL)-1, IL-6, the IL-2 receptor, interferon gamma, tumor necrosis factor-alpha, and IL-6 to induce a cytotoxic response." (PMID 35897819, 2022). "Moreover, NE stimulates fibroblasts metaplasia into myofibroblasts, which provide increased tumour cells motility and increased neoangiogenesis along with the release of protumourigenic cytokines, such as FGF-2, IL-6, IL-8, and VEGF." (PMID 35334544, 2022). "In this study, we did not observe any significant difference of primary tumor growth and the lung metastasis in the mice receiving different inhaled anesthetics after surgery, nor in the levels of pro-inflammatory cytokines (IL-6, MCP-1, CCL-1, or VEGF)." (PMID 35222023, 2022). "To deeply investigate irAEs after aPD-L1 treatment in 4T1 tumor-bearing mice, we detected the infiltrated immune cells (T cells and macrophages) and the inflammatory cytokines (TNF-α, IFN-γ, and IL-6) in major organs (including heart, liver, lung, and kidney) after 2 days post-injection." (PMID 35710545, 2022). "According to the IHC/IF staining of the tumor samples obtained at 6 h, 24 h, 72 h and 7d after RFA, we found significant changes with time manner in different groups on the pathological findings including HSP70, CD31, SMA, Ki-67, c-Met, IL-6, VEGF, and HIF-α." (PMID 35710408, 2022). "Previous studies have demonstrated that some of the proinflammatory cytokines, such as leptin, IL-6, and TNF-α, in the tumor microenvironment could promote tumor progression." (PMID 36361525, 2022). "Several stimuli, such as microbial pathogens, carcinogens, endotoxins, free radicals, interleukin 1 (IL-1), interleukin 6 (IL-6), lipopolysaccharide (LPS), tumor-necrosis factor (TNF), tumor promoter, and radiation (UV-light, X-rays, γ-rays), trigger the activation of NF-κB." (PMID 35408483, 2022). "Interestingly, we observed high concordance of immune analysis results for HELLS with CXCL2 and IL6, revealing for the first time a possible immunological effect of HELLS in tumor." (PMID 34982796, 2022). "Moreover, this biocomplex regulated the secretion of tumor-related cytokines (i.e., GM-CSF, TNF, and IL-6) and promoted the activation of immune cell surface markers (i.e., CD80+, CD86+, and CD40+)." (PMID 36059807, 2022).